RNF39 (ring finger protein 39)
Description:
Plays an inhibitory role in anti-RNA viral innate immunity by targeting the adapter DDX3X and promoting its 'Lys-48'-linked polyubiquitination. Alternatively, enhances the cGAS-STING pathway activation by promoting 'Lys-63'-linked ubiquitination of STING1, facilitating the STING1-TBK1 complex formation and STING1 activation. (Microbial infection) Plays a positive role in human immunodeficiency virus (HIV-1) replication.
Synonyms: HZFW; HZFw1; LIRF; FAP216; HZF
Tractability: Antibody: the Human Protein Atlas places it where antibodies can reach.
Gene: Protein-coding gene on chromosome 6 (30,070,266 to 30,075,849, reverse strand). Ensembl gene ENSG00000204618.
Subcellular location: Cytoplasm
Subcellular location (Human Protein Atlas): Centrosome; Plasma membrane; Vesicles
Gene Ontology:
Molecular function: protein binding; ubiquitin protein ligase activity
Biological process: negative regulation of cytoplasmic pattern recognition receptor signaling pathway; positive regulation of cGAS/STING signaling pathway; protein K63-linked ubiquitination; innate immune response; protein ubiquitination
Cellular component: cytoplasm
Genetic constraint (gnomAD): Loss-of-function variants: 22 observed, 16.49 expected, observed/expected ratio (o/e) 1.33, 90% interval 0.95 to 1.83. The synonymous counts are far from expectation, so gnomAD's model fits this gene poorly and the ratio says little. Missense variants: 510 observed, 359.91 expected, observed/expected ratio (o/e) 1.42, 90% interval 1.32 to 1.52. Synonymous variants: 217 observed, 152.28 expected, observed/expected ratio (o/e) 1.42, 90% interval 1.27 to 1.6.
Homologues: Orthologues: chimpanzee RNF39 (99% identical), pig RNF39 (88% identical), dog RNF39 (86% identical), mouse Rnf39 (83% identical), macaque RNF39 (79% identical), rabbit RNF39 (59% identical), rat Rnf39 (46% identical). Paralogues in human: TRIM7 (32% identical), TRIM41 (31% identical), TRIM27 (31% identical), TRIM11 (30% identical), TRIM39 (30% identical), TRIM21 (29% identical), TRIM72 (29% identical), TRIM58 (28% identical), TRIM26 (27% identical), TRIM4 (27% identical), TRIM50 (27% identical), TRIM10 (27% identical), and 68 more.
Diseases named in the same sentence as RNF39 in open-access papers:
RNF39 is named in the same sentence as 31 diseases in open-access papers, as found by Europe PMC text mining. Sharing a sentence is not in itself a finding about the gene and the disease. The quoted sentences say what the papers report.
AIDS (4 papers, 2008 to 2019). A syndrome resulting from the acquired deficiency of cellular immunity caused by the human immunodeficiency virus (HIV). "We conducted a genetic association study to identify ZNRD1 and RNF39 genetic variants associated with AIDS progression in HIV-1-infected Han Chinese patients residing in Taiwan." (PMID 23874430, 2013). "Due to increased power, the ZNRD1/RNF39 candidate locus was for the first time significantly associated with AIDS progression (P = 1.8 × 10−8)." (PMID 23750159, 2013). "We aimed to identify ZNRD1 and RNF39 genetic variants linked to AIDS progression." (PMID 23874430, 2013). "Finally, a set of chromosome 6 SNPs in the ZNRD1/RNF39 locus was associated with AIDS progression independently from the HCP5 rs2395029 and −35 kb HLA-C signals." (PMID 23750159, 2013). "Also implicated as major determinants of AIDS progression rates were seven SNPs in and around the genes encoding ring finger protein 39 (RNF39) and zinc ribbon domain–containing 1 (ZNRD1), which are in close proximity to the HLA-A locus." (PMID 18982067, 2008). "Among these identified candidate genes, a locus on human chromosome 6, close to the ZNRD1 (zinc ribbon domain-containing 1) and RNF39 (ring finger protein 39) genes, shows an interesting correlation with AIDS progression." (PMID 23874430, 2013). "Effects of ZNRD1and RNF39 gene SNPs on AIDS progression of HIV-1 patients in a Han Chinese population in Taiwan." (PMID 23874430, 2013).
Behcet disease (2 papers, 2019 to 2021). A chronic, relapsing, multisystemic vasculitis characterized by mucocutaneous lesions, as well as articular, vascular, ocular and central nervous system manifestations. "RNF39 encoded a member of ring finger proteins, which was studied in Behcets disease, a chronic inflammatory autoimmune disease." (PMID 31687280, 2019). "Genetic variants of RNF39 are associated with a variety of viral diseases and autoimmune diseases, such as the progression of HIV-1 and Behcet’s disease (BD, a chronic systemic vasculitis resulting in ulcerative in the oral cavity and on the genitals, as well as inflammatory damage of the eyes)." (PMID 34177938, 2021).
depression (2 papers, 2023). "In the follow-up study, we will conduct further researches on RNF39 in AS patients with depression to provide more clinical evidence." (PMID 37746958, 2023). "RNF39 was the most significant DMR in two of the four analyses and has previously been associated with general cognitive function and bipolar and major depressive disorders." (PMID 37258616, 2023).
systemic lupus erythematosus (2 papers, 2017 to 2023). An autoimmune multi-organ disease typically associated with vasculopathy and autoantibody production. "In addition, hypermethylation of 11 CpGs sites within RNF39 was seen in naïve CD4+ T cells of patients with systemic lupus erythematosus (SLE) who had a history of discoid rash." (PMID 28729889, 2017).
allergic rhinitis (1 paper, 2017). Inflammation of the nasal mucous membranes caused by an IgE-mediated response to external allergens. "We also identified 11 genes with marginally significant cis-mQTLs (p < 0.05) including one with both allergic rhinitis with or without asthma (RNF39)." (PMID 28149331, 2017).
autoimmune disease (1 paper, 2021). A disorder resulting from loss of function or tissue destruction of an organ or multiple organs, arising from humoral or cellular immune responses of the individual to their own tissue constituents. "The DNA methylation state of RNF39 impacts autoimmune disorders, including MS, SLE and allergic rhinitis (AR, a delayed hypersensitivity nasal mucosa reaction to environmental allergens, caused by IgE mediated release of autacoids) and confers poor responsiveness to HBV vaccination." (PMID 34177938, 2021).
breast carcinoma (1 paper, 2021). "We used Taqman qPCR to investigate the correlation between the differential methylation of IRF6, SLFN12, and RNF39 with their gene expression at baseline and after the first cycle of DOX chemotherapy in PBMCs of breast cancer patients." (PMID 34944912, 2021).
colorectal cancer (1 paper, 2026). A primary or metastatic malignant neoplasm that affects the colon or rectum. "Functionally, loss‐of‐function perturbation of RNF39 in colorectal cancer cells profoundly attenuated proliferative capacity, invasive behaviour and xenograft tumour growth, whereas enforced RNF39 expression reinforced these malignant traits." (PMID 41457280, 2026). "Collectively, these in vitro data indicate that modulation of RNF39 expression significantly influences key tumour‐associated phenotypes in colorectal cancer cells, including proliferation, clonogenicity and invasive behaviour." (PMID 41457280, 2026). "While RNF43 and RNF183 have been previously implicated in colorectal cancer progression, the consistent and significant elevation of RNF39, a comparatively understudied member of this protein family, suggests it may function as a novel and distinct regulator in COAD pathogenesis." (PMID 41457280, 2026). "Silencing of RNF39 significantly suppressed colorectal cancer cell proliferation, invasion and tumour growth in xenograft models, while ectopic RNF39 expression enhanced these malignant phenotypes." (PMID 41457280, 2026). "In this study, we characterize RNF39, a RING‐type E3 ligase previously linked to immune regulation, as a novel oncogenic regulator in colorectal cancer." (PMID 41457280, 2026). "To provide an integrated mechanistic view of our findings, we developed a schematic model summarizing the molecular pathway by which RNF39 regulates colorectal cancer cell proliferation via RINT1‐mediated ER stress responses." (PMID 41457280, 2026). "In summary, our study establishes RNF39 as a critical mediator of colorectal cancer progression through its regulation of RINT1 stability and ER stress responses." (PMID 41457280, 2026). "Together, these results support the conclusion that RINT1 is a direct substrate of RNF39‐mediated ubiquitination and proteasomal degradation in our colorectal cancer models." (PMID 41457280, 2026). "While this study provides a mechanistic framework connecting RNF39 to ER stress modulation and colorectal cancer development, several questions remain." (PMID 41457280, 2026). "In this study, we identify RNF39 as a previously uncharacterized RING‐type E3 ubiquitin ligase that drives colorectal cancer progression by promoting ubiquitin–proteasome–mediated degradation of RINT1 and dampening ER stress–induced apoptosis." (PMID 41457280, 2026). "We provide mechanistic insight into the subversion of ER stress by colorectal cancer cells and identify RNF39 as a tractable target for therapy." (PMID 41457280, 2026). "Therapeutically, targeting RNF39 or disrupting its interaction with RINT1 could sensitize colorectal cancer cells to chemotherapy and ER stress–based treatments." (PMID 41457280, 2026). "Colorectal cancer cells, which are frequently exposed to hypoxia, nutrient limitation and inflammatory cytokines within the tumour microenvironment, may co‐opt immune‐related E3 ligases such as RNF39 to fine‐tune ER homeostasis and evade stress‐induced apoptosis." (PMID 41457280, 2026).
colorectal tumours (1 paper, 2026). "Notably, RNF39 has been implicated in immune regulation through modulation of antiviral and innate immune signalling pathways, and its dual role in proteostasis and immune signalling may contribute to immune evasion mechanisms in colorectal tumours." (PMID 41457280, 2026).
coronary artery disease (1 paper, 2018). "HLA-J is a pseudogene of HLA-A,59 a gene associated with Graves’ disease, an autoimmune-metabolic disorder of the thyroid gland while RNF39 SNP has recently been associated with non-obstructive coronary artery disease." (PMID 29188820, 2018).
food allergy (1 paper, 2025). Gastrointestinal disturbances, skin eruptions, or shock due to allergic reactions to allergens in food. "This may be related to a differential expression, suggesting that RNF39 could indicate an important role in the development of food allergy or immune tolerance." (PMID 41394805, 2025).
glioma (1 paper, 2024). A benign or malignant brain and spinal cord tumor that arises from glial cells (astrocytes, oligodendrocytes, ependymal cells). "Decreased expression of RNF39 has been associated with lower survival probability in patients with glioma, with expression levels negatively correlated with WHO glioma tumor grade." (PMID 39766155, 2024).
Hepatitis (1 paper, 2017). Inflammation of the liver. "However, one study did reveal an association with hepatitis B vaccination response which suggests that future, larger scale studies of RNF39 and MS should attempt to include factors such as EBV as covariates in the analysis." (PMID 28729889, 2017).
HIV-1 infection (1 paper, 2014). The type species of lentivirus and the etiologic agent of acquired immunodeficiency syndrome (AIDS). "The cDNA overexpression method was further used to evaluate the effect of several proteins on HIV-1 infection after RNF39 knockdown by siRNA." (PMID 25126410, 2014). "Next, RNF39 role in HIV-1 infection was also confirmed by overexpressing RNF39 cDNA in 293 T cells." (PMID 25126410, 2014).
lymph node metastasis (1 paper, 2026). "A similar trend was observed when samples were grouped by lymph node metastasis status, with increased RNF39 expression across N0, N1 and N2 categories." (PMID 41457280, 2026).
mucinous adenocarcinoma (1 paper, 2026). An invasive adenocarcinoma composed of malignant glandular cells which contain intracytoplasmic mucin. "Representative cases of RNF39 overexpression across different histological subtypes, including tubular adenocarcinoma (Cases 1–4), mucinous adenocarcinoma (Case 5) and signet‐ring cell carcinoma (Case 6)." (PMID 41457280, 2026).
multiple sclerosis (1 paper, 2019). A progressive autoimmune disorder affecting the central nervous system resulting in demyelination. "Additionally, hypermethylation of the MHC locus RNF39 has been found to be associated with multiple sclerosis, accounting for a portion of risk independent from the well-stablished susceptibility conferred by HLA-DRB153." (PMID 30718669, 2019).
post-traumatic stress disorder (1 paper, 2021). An anxiety disorder precipitated by an experience of intense fear or horror while exposed to a traumatic (especially life-threatening) event. "RNF39 was found to be differentially expressed in rodent brains exposed to methylmercury, and differential methylation of RNF39 has been associated with schizophrenia spectrum disorders and post-traumatic stress disorder." (PMID 34798907, 2021).
psoriasis (1 paper, 2015). An autoimmune condition characterized by red, well-delineated plaques with silvery scales that are usually on the extensor surfaces and scalp. "Some of the DMRs situated on chromosome 6were in major histocompatibility complex genes, such as ring finger protein 39(RNF39), psoriasis susceptibility 1 candidate 3(PSORS1C3), and HLA complex group 4b (HCG4P6)." (PMID 29492281, 2015).
tumor (3 papers, 2022 to 2026). "RNF39 was previously linked to immune signalling but is co‐opted by tumour cells to regulate ER stress and survival in COAD." (PMID 41457280, 2026). "Crucially, the anti‐tumour phenotypes of RNF39 loss were partially reversed by simultaneous RINT1 knockdown." (PMID 41457280, 2026). "In the multivariable model, advanced tumour stage and high RNF39 expression remained significantly associated with poorer overall survival, indicating that RNF39 acts as an independent unfavourable prognostic factor in COAD." (PMID 41457280, 2026). "Similarly, downregulated genes identified in Cluster 1 have been previously associated with more aggressive tumor characteristics and higher tumor grade; these include RNF39, ADAMTS8, SLC25A42, ST3GAL5, and ZBED3." (PMID 39766155, 2024). "Tumour volume measurements over 4 weeks revealed that RNF39 silencing significantly suppressed tumour growth, while co‐silencing of RINT1 with RNF39 restored tumorigenic potential." (PMID 41457280, 2026). "Overall, RNF39 protein expression was significantly elevated in tumour tissues relative to adjacent normal tissues, as determined by immunohistochemical staining and H‐score." (PMID 41457280, 2026). "Further, t‐test analysis of RNF39 expression H‐scores between adjacent normal tissues and tumour tissues showed statistical significance." (PMID 41457280, 2026). "Quantification of staining scores in matched samples further supported increased RNF39 protein expression in tumour tissues." (PMID 41457280, 2026). "RNF39 transcript levels were elevated in tumour samples at stages I through IV compared to normal tissues." (PMID 41457280, 2026). "Tumour mass at endpoint was also significantly reduced in the RNF39 knockdown group, and this reduction was reversed upon RINT1 depletion." (PMID 41457280, 2026). "By linking transcriptional control with ubiquitin‐dependent proteolysis, RNF39 enables tumour cells to maintain ER homeostasis and evade stress‐induced apoptosis." (PMID 41457280, 2026). "RINT1 acts as a functional downstream effector of RNF39, integrating proteostasis regulation with tumour growth and survival signalling." (PMID 41457280, 2026). "Among 33 tumour types analysed, elevated RNF39 transcript levels were observed in COAD compared to normal tissues." (PMID 41457280, 2026). "Cross‐cancer analyses could reveal whether RNF39‐driven degradation of RINT1 or other substrates is a generalizable mechanism co‐opted by tumour cells to bypass ER stress‐induced apoptosis." (PMID 41457280, 2026). "From a translational perspective, RNF39 overexpression correlates with poor prognosis and could serve as a biomarker for stress‐adaptive tumour phenotypes." (PMID 41457280, 2026). "Endpoint measurements confirmed significantly lower tumour weights in the RNF39−/− cohort." (PMID 41457280, 2026). "RNF39−/− xenografts exhibited a markedly reduced tumour volume relative to WT controls." (PMID 41457280, 2026). "Given the established link between ER stress, immune modulation and tumour adaptation, RNF39 may represent a molecular bridge integrating stress and immune signalling in cancer." (PMID 41457280, 2026). "We show that RNF39 is transcriptionally activated by MEF2D and enhances tumour cell proliferation and invasion by suppressing RINT1 accumulation, thereby attenuating UPR activation and preventing ER stress‐induced apoptosis." (PMID 41457280, 2026). "RNF39 mRNA expression was significantly upregulated in tumour tissues across multiple datasets: GSE23878 (tumour n = 35, normal n = 24), GSE32323 (tumour n = 17, normal n = 17) and GSE110225 (tumour n = 17, normal n = 17)." (PMID 41457280, 2026). "The oncogenic effects of RNF39 on COAD cells − enhancing proliferation, invasion and tumour growth − are attributable to its E3 ubiquitin ligase function." (PMID 41457280, 2026). "Functionally, RNF39 promoted COAD cell proliferation and invasion in vitro and tumour growth in vivo, dependent on its E3 ligase activity." (PMID 41457280, 2026).
tumor (continued). "Immunohistochemistry of ADAMTS1, DSC1, RNF39, CD3 and LDB3 was performed to evaluate protein expression in tumor cells." (PMID 36333410, 2022). "This transcriptional link integrates RNF39 into a broader oncogenic regulatory network, where MEF2D acts as a nodal point coordinating transcriptional and post‐translational pathways that support tumour cell survival." (PMID 41457280, 2026). "To assess whether RNF39 is an independent prognostic factor in COAD, we performed Cox proportional hazards analysis in the TCGA‐COAD cohort using age, gender, tumour stage, MSI status and RNF39 expression as covariates." (PMID 41457280, 2026). "Second, given the complexity of ER stress signalling, it will be important to determine whether RNF39 selectively modulates specific branches of the UPR (e.g. PERK–eIF2α–CHOP vs. ATF6 or IRE1) and how this regulation impacts tumour cell fate decisions." (PMID 41457280, 2026).
cancer (2 papers, 2014 to 2026). A tumor composed of atypical neoplastic, often pleomorphic cells that invade other tissues. "To further assess RNF39 expression patterns in human malignancies, we performed a pan‐cancer transcriptomic analysis based on TCGA and GTEx datasets." (PMID 41457280, 2026). "Despite its inclusion in this family, the function of RNF39 has remained largely unexplored in cancer." (PMID 41457280, 2026). "Although RNF39 has primarily been characterized in the context of immune regulation and viral response, its potential involvement in cancer biology may derive from its broader role in ubiquitin‐dependent proteostasis." (PMID 41457280, 2026). "Although prior work highlights the immunomodulatory capacity of RNF39, whether it governs proteostasis or ER stress in cancer − especially in epithelial tumours such as COAD − remains unclear." (PMID 41457280, 2026). "The protein coding genes ZNRD1, RNF39 and PPP1R11, along with the ncRNA ZNRD1-AS1, have been associated with disease states that are related to autoimmunity, immunity, and infection; while EPM2A and SHPRH have been associated with glycogen metabolism, cancer, and chemical dependency." (PMID 25642351, 2014).
RNF39 also shares sentences with these, for which no sentence is quoted: asthma (1 paper); chickenpox (1); Graves disease (1); infection (1); Insulin resistance (1); metastatic tumors (1); mononucleosis (1); Obesity (1); rheumatoid arthritis (1); tubular adenocarcinoma (1).